MPO (myeloperoxidase)
Diseases named in the same sentence as MPO in open-access papers (continued):
Sharing a sentence is not in itself a finding about the gene and the disease.
autoimmune hypothyroidism (2 papers, 2014 to 2024). "Laboratory investigations demonstrated inflammatory anemia, elevated erythrocyte sedimentation rate, mild proteinuria, autoimmune hypothyroidism, and positive p-ANCA-myeloperoxidase (MPO) with a nuclear-dense anti-nuclear antibodies (ANA) pattern." (PMID 39872577, 2024).
axonal neuropathy (2 papers, 2024 to 2025). Any nerve disorder affecting the axon of a nerve. "Diagnostic criteria were met, including positive anti-neutrophil cytoplasmic antibody (ANCA) with myeloperoxidase (MPO) pattern and severe axonal neuropathy confirmed by nerve biopsy." (PMID 39606502, 2024).
bipolar disorder (2 papers, 2020 to 2023). A disorder of the brain that causes unusual shifts in mood, energy, activity levels and the ability to carry out day-to-day tasks. "While we believe that this is the first study to observe this relationship in PTSD, MPO has been positively correlated with duration of bipolar disorder, and higher MMP-9 has been reported in younger youth diagnosed with bipolar disorder compared to older adults." (PMID 37333909, 2023).
bladder tumor (2 papers, 2023 to 2024). "However, this is the first time a ratio between a supposed protective protein (cubilin) and a cancer aggressiveness promoter (MPO) measured in the urine of patients has been studied as a prognostic risk factor to predict recurrence and progression to muscle-invasive T1 bladder tumours." (PMID 38530585, 2024). "Here, we demonstrated that the mean ratio value of CUBN/MPO was significantly lower if patients had experienced bladder tumour recurrence or progression." (PMID 38530585, 2024). "The percent of patients with CitH3+HMGB3+ and CitH3+MPO+ was further quantified in the two breast, two lung as well as one bladder tumor tissue arrays." (PMID 36973439, 2023).
Brain atrophy (2 papers, 2006 to 2022). Partial or complete wasting (loss) of brain tissue that was once present. "In a recent work Zakrewska-Pniewska and co-workers analysed the relationship between APOE and MPO genes' polymorphisms and MS, and they found that the genotype GG of MPO was related to more pronounced brain atrophy." (PMID 16504169, 2006).
brain inflammation (2 papers, 2017 to 2023). "We observe that treatment with FeTPPS (30 mg/kg, i.p.)reduced: the state of brain inflammation and the tissue hurt (histological score), myeloperoxidase activity, nitric oxide production, glial fibrillary acidic protein (GFAP) and pro-inflammatory cytokines expression and apoptosis process." (PMID 28223911, 2017).
breast tumors (2 papers, 2023 to 2025). "We found that MPO-expressing TANs and non-neutrophils (monocyte/macrophages) in the primary breast tumors (PT), were associated with a worse prognosis in MBC patients." (PMID 40652059, 2025). "Levels of malondialdehyde MDA (end-product of lipid peroxidation), myeloperoxidase MPO activity (lysosomal oxidising agent) and nitric oxide (inflammatory marker), that were significantly increased in Wistar rats bearing breast tumours, were ameliorated in rats treated with nanoceria." (PMID 36656411, 2023).
bronchopulmonary dysplasia (2 papers, 2022 to 2024). Bronchopulmonary dysplasia is a chronic respiratory disease that results from complications related to lung injury during the treatment of infant acute respiratory distress syndrome in low-birth-weight premature infants or from abnormal lung development in older infants. "Myeloperoxidase (MPO), oxidative stress (OS), and endoplasmic reticulum (ER) stress are increased in the lungs of rat pups raised in hyperoxia, an established model of bronchopulmonary dysplasia (BPD)." (PMID 36018859, 2022).
cardiac hypertrophy (2 papers, 2022). "MPO is an inflammatory enzyme, and its release has been associated with cardiac hypertrophy and continuous activation and recruitment of leukocytes to infarcted tissue." (PMID 35186101, 2022). "The ability of extracts to prevent cardiac hypertrophy could therefore be ascribed to their anti-inflammatory effects especially their action against MPO." (PMID 35186101, 2022).
cerebritis (2 papers, 2019 to 2024). Inflammation of the cerebrum. "To assess our platform for imaging ex vivo tissue blocks and sections, we next induced focal cerebritis in the brains of wildtype and MPO-KO mice by intracerebral injection of salmonella." (PMID 31695784, 2019). "Indeed, we found similar results in a mouse model of cerebritis using an MPO activatable biotinylated sensor." (PMID 39325942, 2024). "Within the region of cerebritis, we detected both MPO protein and MPO activity, but the two did not completely overlap." (PMID 31695784, 2019). "Interestingly, in an area of normal appearing brain a short distance from the region of cerebritis in the ipsilateral hemisphere, we detected cells that stained positively for MPO protein but demonstrated no appreciable MPO activity." (PMID 31695784, 2019).
Chagas disease (2 papers, 2013 to 2018). A parasitic infection caused by Trypanosoma cruzi. "Our finding of a significant linear correlation between MPO and clinically-symptomatic disease provide the first evidence for the pathological significance of increased MPO activity in Chagas disease, and potential use of this biomarker in diagnosing disease severity." (PMID 23951383, 2013). "Finally, we examined peripheral and myocardial parasite burden, plasma levels of myeloperoxidase and IL-6, and myocardial inflammatory infiltrate and LDH expression to evaluate the effect of parasite and MnSOD deficiency on inflammatory stress in Chagas disease." (PMID 30044789, 2018). "The MPO, LPO and nitrite are excellent biomarkers for diagnosing seropositive/chagasic subjects, and MPO and LPO levels have potential utility in identifying clinical severity of Chagas disease." (PMID 23951383, 2013). "The finding of a significant correlation between the increase in MPO and LPO levels and clinical Chagas disease in this study provide us an impetus to test and verify the sensitivity and specificity of MPO and LPO in determining clinical Chagas disease in large-scale cross-sectional studies." (PMID 23951383, 2013).
childhood asthma (2 papers, 2023 to 2024). "This study investigated the relationship between the expression of MPO and HNL/NGAL and childhood asthma." (PMID 39448961, 2024).
cholera (2 papers, 2018 to 2022). "Intriguingly, among older children in Bangladesh, elevated MPO was associated with improved responses to an oral cholera vaccine." (PMID 29926747, 2018). "Thus, we examined two common fecal markers of intestinal inflammation (MPO) and permeability (AAT), and found a high heterogeneity among cholera patients." (PMID 35551522, 2022).
chronic myeloid leukemia (2 papers, 2015 to 2017). "We have previously shown that TKIs such as dasatinib and imatinib also reduce the presence of MDSCs and suppressive factors such as MPO and Arginase I in patients with chronic myeloid leukemia (CML)." (PMID 26561829, 2015). "As expected, SA pretreatment did not affect stabilized TOP2A or TOP2B-DNA complexes in K562 cells, a chronic myeloid leukemia-derived cell line that does not express MPO." (PMID 27974636, 2017). "K562 is a chronic myeloid leukemia derived cell line that does not express detectable MPO." (PMID 27974636, 2017).
colon adenocarcinoma (2 papers, 2016 to 2022). "In line with previous reports indicating the presence of NETs in cancer biopsies, we showed abundance of NETs in colon adenocarcinoma sections both within the primary tumour and in metastatic lymph nodes, as extracellular colocalizations of neutrophil elastase with citrullinated histone H3 or MPO." (PMID 27136460, 2016).
Colonic disease (2 papers, 2009 to 2019). "Colonic disease was assessed at 8 weeks in Ussing chambers, and at 17 weeks of age inflammatory cytokines and myeloperoxidase were measured in the colon." (PMID 18829978, 2009). "The main evaluation indices used were the colonic disease activity index (DAI), colon length, spleen coefficient, myeloperoxidase (MPO) activity, pathological damage assessment, and the expression levels of IL-4, IL-13, and TNF-α." (PMID 31878303, 2019).
colorectal adenoma (2 papers, 2022 to 2023). An adenoma that arises from the colon or rectum. "In another study involving a mouse colorectal adenoma model, 6-shogaol treatment reversed the effect of Azoxymethane (AOM) and dextran sulphate sodium (DSS) in animal models by reducing colon weight, colon length, and the levels of NO, myeloperoxidase (MPO), H2O2, and TNF-α." (PMID 37570837, 2023).
contact dermatitis (2 papers, 2015 to 2021). An inflammatory skin condition caused by direct contact between the skin and either an irritating substance or an allergen. "Topical DAPS is more effective than DHPS in preventing inflammatory signs (increased vascular permeability, edema, leukocyte infiltration, MPO activation) caused by contact dermatitis induction in rat ears." (PMID 25638171, 2015). "They found that CA has anti-inflammatory activities in both acute and chronic contact dermatitis models through blocking of mRNA and protein synthesis of the cytokines, such as TNF-α, IL-6, and IL-1β, and neutrophil-mediated myeloperoxidase activity." (PMID 34040528, 2021).
deafness (2 papers, 2012 to 2024). An inherited or acquired condition characterized by the complete loss of the ability to hear from one or both ears. "Among the overlapped DEGs and ASGs, we found two and one hearing loss/deafness genes in R. affinis himalayanus (MMP9 and MPO) and R. sinicus (TPM2), respectively." (PMID 38672325, 2024). "Her vertigo and deafness were likely the results of CSS exacerbation or late flare-up, which was evidenced by rising titers of MPO-ANCA and inflammatory markers." (PMID 22989316, 2012).
dengue (2 papers, 2018 to 2021). "Using a scatterplot quadrant analysis, samples from the early phases of dengue (day 1-3 and day 4-6) were generally positive in both the total NETs and MPO-H4K8Ac, K12Ac, K16Ac ELISA (NOX-independent NETs), suggesting that NETs were predominantly NOX-independently generated." (PMID 34122402, 2021). "To determine whether NETs were produced during Dengue virus infection, and the association of NETs with clinical outcomes of DENV infection, we measured the level of MPO-DNA complexes in the serum of DENV-infected patients by ELISA." (PMID 30687301, 2018).
dental caries (2 papers, 2018 to 2023). The decay of a tooth, in which it becomes softened, discolored, and/or porous. "The results showed a significant decrease (0.94±0.34) (p≤0.05) in MPO in patients with severe dental caries and positive culture for Lactobacillus compared to the control group (1.07±0.34) (p≤0.05)." (PMID 37900082, 2023). "There was a significant decrease (p≤0.05) in myeloperoxidase levels in patients with severe dental caries and positive Lactobacillus culture compared to the control group." (PMID 37900082, 2023).
diabetic neuropathy (2 papers, 2022 to 2025). A chronic, pathological complication associated with diabetes mellitus, where nerve damages are incurred due to diabetic microvascular injury involving small blood vessels that supply these nerves, resulting in peripheral and/or autonomic nerve dysfunction. "In addition, overproduction of metabolites of oxidative stress, such as myeloperoxidase, superoxide dismutase-3, thiobarbituric acid reactive substances (TBARS) and methylglyoxal, were improved to be with progression of diabetic neuropathy." (PMID 35093139, 2022).
erectile dysfunction (2 papers, 2023 to 2024). Persistent or recurrent inability to achieve or to maintain an erection during sexual activity. "Also, many clinicalstudies have linked myeloperoxidase and its modified LDL product to multipleatherosclerosis-related diseases including erectile dysfunction and kidneyfailure." (PMID 39077081, 2023). "Finally, the main MPO byproduct, MPO-oxidized LDL (Mox-LDL), has been reported to be involved in the pathogenesis of several important disease states that are related to kidney inflammation and failure, erectile dysfunction and sleep disorders." (PMID 39201490, 2024).
esophageal cancer (2 papers, 2001 to 2024). A primary or metastatic malignant neoplasm involving the esophagus. "In this study, we found the MPO -463 G/A polymorphism to be linked to esophageal cancer susceptibility, especially among the older age population more significantly affected by smoking." (PMID 11434421, 2001). "In the present study, we therefore conducted a hospital-based case control study to evaluate any association between esophageal cancer and the MPO polymorphism." (PMID 11434421, 2001). "A -463 G/A polymorphism in the promoter region of the MPO gene results in reduced gene expression, which would imply lower susceptibility of esophageal cancer in mutant carriers." (PMID 11434421, 2001). "Although there are limitations for interpretation of this study because of prevalent case-control study and partial statistical significance, these results suggest that MPO -463 A allele reduce the risk of esophageal cancer." (PMID 11434421, 2001). "In summary, this study revealed that esophageal cancer risk for individuals with the MPO -463 A allele was reduced, especially in the aged, although a part of the effect might be related to the prognosis." (PMID 11434421, 2001).
falciparum malaria (2 papers, 2018 to 2023). "MPO and neutrophils have been implicated in the pathogenesis of falciparum malaria." (PMID 30563486, 2018). "However, very few studies have analyzed MPO levels in human falciparum malaria." (PMID 30563486, 2018). "The implication of MPO in falciparum malaria severity is not well elucidated but reported that myeloperoxidase production increased during malaria parasite infection and correlated it with parasite clearance." (PMID 36658587, 2023). "MPO release has more recently been related to NET formation that could have anti-parasitic effects, but NETs could also promote vascular pathology during falciparum malaria, illustrating the immune response as a double edge sword during falciparum malaria." (PMID 30563486, 2018).
fibromyalgia (2 papers, 2022 to 2023). A chronic disorder of unknown etiology characterized by pain, stiffness, and tenderness in the muscles of neck, shoulders, back, hips, arms, and legs. "When we compared PR3- and MPO-ANCA fatigued patients, MPO-AAV-CFS patients had more similarities with fibromyalgia patients than PR3-AAV-CFS." (PMID 36890852, 2023). "Pain as measured by the WPI, was lower in PR3- and MPO-AAV-CFS patients than in fibromyalgia controls (p < 0.001)." (PMID 36890852, 2023). "We hypothesize that a large proportion of AAV patients will fulfil the diagnostic criteria for both ME/CFS and fibromyalgia and that differences will be found between PR3 and MPO patients." (PMID 36890852, 2023). "Separating fatigued AAV patients by serotype (PR3-ANCA n = 11; MPO-ANCA n = 16), and comparing them to fibromyalgia controls, revealed several notable differences between the two groups." (PMID 36890852, 2023). "Rates of fatigue were higher in MPO-ANCA patients, than in PR3-ANCA patients, and their symptoms were more similar to the fibromyalgia controls." (PMID 36890852, 2023). "MPO-AAV-CFS patients also had higher levels of pain than PR3-AAV-CFS patients, and higher rates of comorbid fibromyalgia." (PMID 36890852, 2023).
fluorosis (2 papers, 2015 to 2019). "Recently, it was noticed that the myeloperoxidase gene polymorphism was related with fluorosis in adults living in the coal-burning endemic fluorosis area in Guizhou of China." (PMID 26046522, 2015).
gastric adenocarcinoma (2 papers, 2022 to 2025). "Differential gene enrichment analysis between high and low MPO expression groups in TCGA gastric adenocarcinoma revealed that these DEGs were significantly associated with key biological processes, cellular components, molecular functions, and signaling pathways." (PMID 40547041, 2025). "The results indicated that high MPO expression was significantly associated with poor survival prognosis, particularly in disease-specific events, where high MPO expression was closely linked to disease progression in gastric adenocarcinoma." (PMID 40547041, 2025). "Given that high MPO expression is associated with poor prognosis in gastric adenocarcinoma, MPO could potentially serve as a prognostic biomarker for gastric adenocarcinoma patients." (PMID 40547041, 2025). "Second, while we observed a correlation between MPO expression and gastric adenocarcinoma prognosis, the underlying mechanisms remain unclear, and further investigation is needed to explore MPO’s role in tumor immune escape and progression." (PMID 40547041, 2025). "We analyzed data from 375 gastric adenocarcinoma patients in the TCGA cohort, stratifying them into low (n = 187) and high (n = 188) MPO expression groups." (PMID 40547041, 2025). "In particular, the TCGA cohort represents a broad and diverse patient population, providing a solid foundation for investigating the role of MPO in gastric adenocarcinoma." (PMID 40547041, 2025). "To explore the biological significance of MPO expression in gastric adenocarcinoma, we performed differential gene expression analysis between high and low MPO expression groups." (PMID 40547041, 2025). "In conclusion, future studies should focus on the immune regulatory mechanisms of MPO in healthy populations, while emphasizing the need for further research in gastric adenocarcinoma cohorts." (PMID 40547041, 2025).
gynecological cancers (2 papers, 2013 to 2021). "Uterus IRI resulted in increased MPO levels (7.18% (6.57; 7.75) in the control group, 5.61% (3.58; 6.36) in the melatonin group, 5.31% (4.62; 6.16) in the glycine group and 4.04% (2.86; 5.2) in the combined treatment group)." (PMID 34445081, 2021). "Uterus IRI led to increased myeloperoxidase expression, which was significantly reduced by melatonin (p = 0.004), glycine (p < 0.001) or their combination (p < 0.001)." (PMID 34445081, 2021). "Furthermore, high MPO activity or MPO+ cell infiltration have been detected in esophageal, and gynecological cancers and in CRC, but their prognostic impact was not analyzed." (PMID 23734221, 2013).
hantavirus infection (2 papers, 2021 to 2025). "NETs constituents such as neutrophil elastase, MPO and histones are cytotoxic towards endothelial cells and have been linked to kidney injury in hantavirus infection." (PMID 34122402, 2021). "We report a case of new-onset AAV with MPO-ANCA positivity following hantavirus infection, which presented as an atypical HFRS." (PMID 40527835, 2025). "Here, we present a case of newly diagnosed AAV with MPO-ANCA positivity in a patient with a confirmed hantavirus infection, specifically the Hantaan virus." (PMID 40527835, 2025).
head and neck cancer (2 papers, 2020 to 2022). A primary or metastatic malignant neoplasm affecting the head and neck. "Regarding enzyme association with tumor progression, high MPO expression was associated with distant metastases in head and neck cancers." (PMID 33167555, 2020).
hepatitis B (2 papers, 2012 to 2024). "Subsequent studies were significant for a positive antinuclear antibody (ANA) and myeloperoxidase (MPO) antineutrophil cytoplasmic antibody (ANCA), negative proteinase 3 (PR3) ANCA, normal C3 and C4 complement protein levels, and negative hepatitis B and C serologies." (PMID 39650915, 2024).
hyperamylasemia (2 papers, 2012 to 2018). Abnormally high level of amylase in the blood. "Lactose treatment significantly reduced AP symptoms, including pancreatic edema, hyperamylasemia, and increased pancreatic MPO activities in a time-related manner." (PMID 29719535, 2018).
hypercalcaemia (2 papers, 2018 to 2025). "Hypercalcemia and high serum levels of parathyroid hormone-related protein (PTHrP) and myeloperoxidase-antineutrophil cytoplasmic antibody (MPO-ANCA) titers were observed." (PMID 29548309, 2018).